NHERF1 (NHERF family PDZ scaffold protein 1)
Description:
Scaffold protein that connects plasma membrane proteins with members of the ezrin/moesin/radixin family and thereby helps to link them to the actin cytoskeleton and to regulate their surface expression. Necessary for recycling of internalized ADRB2. Was first known to play a role in the regulation of the activity and subcellular location of SLC9A3. Necessary for cAMP-mediated phosphorylation and inhibition of SLC9A3. May enhance Wnt signaling. May participate in HTR4 targeting to microvilli (By similarity). Involved in the regulation of phosphate reabsorption in the renal proximal tubules. Involved in sperm capacitation. May participate in the regulation of the chloride and bicarbonate homeostasis in spermatozoa.
Synonyms: NHERF-1; EBP50; NHERF; SLC9A3R1; NHE-RF; NPHLOP2
Tractability: Small molecule: it has a binding pocket of medium quality. Antibody: UniProt places it where antibodies can reach, with medium confidence; its Gene Ontology location is reachable by antibodies, with medium confidence; the Human Protein Atlas places it where antibodies can reach. PROTAC: ubiquitination databases record sites on it; a small molecule that binds it is known.
Gene: Protein-coding gene on chromosome 17 (74,748,619 to 74,769,360, forward strand). Ensembl gene ENSG00000109062.
Subcellular location: Cytoplasm; Apical cell membrane; Endomembrane system; Cell projection, filopodium; Cell projection, ruffle; Cell projection, microvillus
Subcellular location (Human Protein Atlas): Centriolar satellite; Plasma membrane; Basal body; Calyx; Centrosome; Cytosol; Vesicles
Gene Ontology:
Molecular function: beta-2 adrenergic receptor binding; beta-catenin binding; channel activator activity; chloride channel regulator activity; growth factor receptor binding; identical protein binding; PDZ domain binding; phosphatase binding; protein binding; signaling receptor binding; type 2 metabotropic glutamate receptor binding; type 3 metabotropic glutamate receptor binding; gamma-aminobutyric acid transmembrane transporter activity; protein-membrane adaptor activity; dopamine receptor binding; molecular adaptor activity
Biological process: establishment of epithelial cell apical/basal polarity; establishment of Golgi localization; gland morphogenesis; maintenance of epithelial cell apical/basal polarity; microvillus assembly; negative regulation of canonical Wnt signaling pathway; negative regulation of cell population proliferation; negative regulation of ERK1 and ERK2 cascade; negative regulation of mitotic cell cycle; negative regulation of phosphatidylinositol 3-kinase/protein kinase B signal transduction; nuclear migration; positive regulation of intrinsic apoptotic signaling pathway; protein localization to plasma membrane; regulation of cell shape; regulation of cell size; renal phosphate ion absorption; bile acid secretion; cerebrospinal fluid circulation; cilium organization; gamma-aminobutyric acid import; glutathione transport; import across plasma membrane; morphogenesis of an epithelium; negative regulation of platelet-derived growth factor receptor signaling pathway; plasma membrane organization; and 5 more
Cellular component: apical plasma membrane; cell periphery; cytoplasm; extracellular exosome; membrane; microvillus; nucleus; perinuclear region of cytoplasm; vesicle; actin cytoskeleton; microvillus membrane; plasma membrane protein complex; sperm midpiece; apical part of cell; brush border membrane; endomembrane system; filopodium; ruffle; stereocilium; stereocilium tip
Genetic constraint (gnomAD): Loss-of-function variants: 24 observed, 25.39 expected, observed/expected ratio (o/e) 0.95, 90% interval 0.68 to 1.33. The upper end of that interval is the gene's LOEUF score, 1.33, which puts it in group 5 of 6, group 1 being the genes least tolerant of losing a copy. Missense variants: 524 observed, 470.94 expected, observed/expected ratio (o/e) 1.11, 90% interval 1.03 to 1.2. Synonymous variants: 221 observed, 201.44 expected, observed/expected ratio (o/e) 1.1, 90% interval 0.98 to 1.23.
Homologues: Orthologues: chimpanzee NHERF1 (99% identical), macaque NHERF1 (97% identical), dog NHERF1 (89% identical), pig NHERF1 (89% identical), guinea pig NHERF1 (89% identical), rat Nherf1 (87% identical), mouse Nherf1 (87% identical), rabbit NHERF1 (80% identical), zebrafish nherf1a (51% identical), tropical clawed frog nherf1 (51% identical), zebrafish NHERF1 (51% identical), Drosophila melanogaster CG10939 (23% identical). Paralogues in human: NHERF2 (48% identical), PDZK1 (32% identical), NHERF4 (28% identical).
Diseases named in the same sentence as NHERF1 in open-access papers:
NHERF1 is named in the same sentence as 126 diseases in open-access papers, as found by Europe PMC text mining. Sharing a sentence is not in itself a finding about the gene and the disease. The quoted sentences say what the papers report.
breast carcinoma (34 papers, 2005 to 2025). "This has been shown in a previous study to be the case with NHERF1, which is frequently mutated in breast cancers, while its complete loss was observed in estrogen receptor-negative cancers." (PMID 37623973, 2023). "The upregulation of NHERF1, as a suggestive poor prognosis indication, was earlier discovered in breast cancers for its association with tumor malignancy and metastatic progression." (PMID 32164629, 2020). "This mutation resulted in a reduced interaction of NHERF1 with the epidermal growth factor receptor, thereby promoting the progression of breast cancer." (PMID 30463370, 2018). "In the present study, a novel NHERF1 sequence variant (TAC to TCC) resulting in a switch of codon 24 (Tyr-Ser) was identified in human breast cancer tissues." (PMID 27097111, 2016). "A novel mutation, namely NHERF1 Y24S, was identified in human breast cancer tissues and shown to correspond to a conserved residue in the PDZ-I domain of NHERF1." (PMID 27097111, 2016). "Overall, it was showed that NHERF1 upregulation was associated with poor prognosis and decreased survival time of patients with breast cancer." (PMID 27097111, 2016). "Truncation and mutation of the PDZ-I domain of NHERF1 increased the nuclear distribution of the NHERF1 protein, and this redistribution was associated with the malignant phenotype of breast cancer cells, including growth, migration, and adhesion." (PMID 27097111, 2016). "In the present study, we found that NHERF1 was upregulated in high grade breast cancer patients and associated with poor prognosis." (PMID 27097111, 2016). "The present results suggest a role for NHERF1 in the progression of breast cancer mediated by the nuclear distribution of the NHERF1 protein, as determined by the truncation or key site mutation of the PDZ-I domain." (PMID 27097111, 2016). "The breast cancer-derived NHERF1 mutation Y24S inactivated the inhibitory effect of NHERF1 on FBS-induced AKT and ERK activation, and resulted in the partial loss of its tumor-suppressor effects." (PMID 27097111, 2016). "If NHERF1 activity is dependent on PTEN, as our functional study had suggested, then intact NHERF1 should be associated with altered PTEN (or PI3KCA) gene in breast cancer." (PMID 18190691, 2008). "Given the contributing role of cyclin E in mammary gland hyperplasia and tumourigenesis, it is conceivable that the deregulation of cyclin E as a result of NHERF1 loss contributes to the breast cancer initiation or progression." (PMID 17078868, 2006). "In addition, GPER protein levels are positively associated with NHERF1 protein levels in a panel of estrogen receptor (ER)-positive breast cancer cells." (PMID 27448983, 2016). "Whether NHERF1 affects breast cancer susceptibility through the haploinsufficiency mechanism requires further investigation." (PMID 18190691, 2008). "Whether the disturbance of mammary gland development as a result of NHERF1 gene loss is sufficient to increase breast cancer incidence needs to be investigated." (PMID 17078868, 2006). "In addition, NHERF1 is mutated in a subset of primary breast tumours and breast cancer cell lines." (PMID 17078868, 2006). "As an established biomarker of endocrine resistance in luminal B breast cancer, NHERF1 coordinates hormone receptor trafficking and G-protein signaling." (PMID 41007409, 2025). "In human tumors, NHERF1 has been found overexpressed in breast cancer, schwannoma, hepatocellular carcinoma and other human tumors." (PMID 35223518, 2022). "From previous reports in breast cancer and cervical cancer cells, NHERF1 was shown to be able to influence the sensitivity of a variety of anti-cancer drugs." (PMID 32164629, 2020). "The upregulation of NHERF1 has been reported in multiple disease states, including hepatocellular carcinomas, cholangiopathies, glioblastoma, breast cancer, psoriasis, and vascular injury." (PMID 33092043, 2020).
breast carcinoma (continued). "In breast cancer, increased cytoplasmic NHERF1 and decreased membranous localization during ductal carcinoma in situ (DCIS) transformed into invasive and metastatic types." (PMID 32164629, 2020). "It was also reported that NHERF1 elicited pharmacologic effect to enhance drug response of geftinib and imatinib in breast cancers." (PMID 32164629, 2020). "NHERF1 interaction partners can be either cytoplasmic or nuclear factors, regulated by a wide range of signals in breast cancer or colorectal cancers, such as VEGFR and HIF-1ɑ, some of which closely associated with lymphatic metastasis." (PMID 32164629, 2020). "Accordingly, recent evidence earmark NHERF1 as an autophagy regulator in breast cancers via its influence on the ubiquitin-dependent degradation of BECN1, a critical component of the autophagic core lipid kinase complex." (PMID 29551770, 2018). "In recent years an association between the scaffolding protein Na+/H+ exchanger regulatory factor 1 (NHERF1) and tumor microenvironment changes in breast cancer (BC) has been reported." (PMID 29716631, 2018). "All breast cancers showed NHERF1 protein localized in the cytoplasm of tumor cells, of these 49% (76/154) overexpressed cNHERF1, according to the median value ≥40%." (PMID 29716631, 2018). "NHERF1 overexpression is associated with high-grade tumors and increased expression of HIF-1 alpha protein in breast cancer." (PMID 28430808, 2017). "It has been recognized that Na+/H+ Exchanger Regulatory Factor 1 (NHERF1) in breast cancer (BC) acts as a tumor suppressor or as an oncogenic protein, depending on its subcellular localization." (PMID 29029467, 2017). "More importantly, NHERF1 also elicited pharmacologic function by enhancing the response of breast cancer cells to anti-cancer drugs such as geftinib and imatinib." (PMID 28085111, 2017). "Transcriptional activation of NHERF1 by hypoxia has also been established in in vitro models, including several breast cancer cell lines." (PMID 28430808, 2017). "Recently, it has been reported that NHERF1 is involved in cancer progression, including breast cancer, hepatocellular carcinoma and glioblastoma." (PMID 27999191, 2017). "In this study, PDZ protein Na+/H+ exchanger regulatory factor (NHERF1) was found to interact with GPER in breast cancer cells." (PMID 27448983, 2016). "NHERF1 is highly expressed in breast carcinoma and positively correlated with tumor size and grade, especially in estrogen receptor (ER)-positive breast carcinoma." (PMID 27448983, 2016). "In the present study, we examined the effects of ectopic nuclear expression of NHERF1 in human breast cancer tissues." (PMID 27097111, 2016). "PSD95 and SAP97 are mainly expressed in the brain and barely expressed in breast epithelium and breast cancer cells, whereas NHERF1 is highly expressed in ER-positive breast cancer cell lines and specimens." (PMID 27448983, 2016). "By analyzing clinical breast cancer data from TCGA, we also found a positive correlation between NHERF1 expression and GPER pathway activation in ER-positive breast cancer." (PMID 27448983, 2016). "In the current study, we investigated the expression pattern and cellular distribution of NHERF1 in human breast cancer tissues." (PMID 27097111, 2016). "In the present finding, we observed that GPER protein levels were positively correlated with the levels of NHERF1 in a panel of breast cancer cells." (PMID 27448983, 2016). "We further showed that NHERF1/Fzd interactions inhibit canonical Wnt signaling in breast cancer cell cultures and in murine breast ducts." (PMID 27055101, 2016). "NHERF1 is reported to suppress breast cancer cell viability when it scaffolds with tumor suppressors, whereas it becomes an oncogenic protein when it interacts with oncoproteins." (PMID 27448983, 2016).
breast carcinoma (continued). "Although studies have investigated the correlation between cytoplasmic overexpression of NHERF1 and oncogenic progression, little is known about the involvement of nuclear NHERF1 in breast cancer." (PMID 27097111, 2016). "Previously, we observed that VEGFR1 was expressed in the cytoplasm of breast cancer cells, where also NHERF1 expression was predominant." (PMID 22439624, 2012). "The PVI+/membranous NHERF1- expression phenotype identifies a category of grade 2 tumors with the worst prognosis, including patient subgroup with a family history of breast cancer." (PMID 22439624, 2012). "In particular, the PVI+/membranous NHERF1- expression immunophenotype identifies a category of grade 2 tumors with the worst prognosis, including patients with a family history of breast cancer." (PMID 22439624, 2012). "Recently, we have demonstrated that the Na+⁄H+ exchanger regulatory factor 1 (NHERF1), an adaptor protein for membrane macromolecular complexes, is a potential candidate of clinical relevance for human breast cancer." (PMID 22439624, 2012). "In support of this mechanism, we found that LOH of NHERF1 locus in 22 breast cancer cell lines was strongly correlated with lowered NHERF1 protein level." (PMID 18190691, 2008). "Because estrogenic signaling is thought to be growth promoting in breast cancer, the suppressor activity of NHERF1 was somewhat unexpected." (PMID 18190691, 2008). "The gene encoding Na+/H+ exchanger regulatory factor 1 (NHERF1) (also known as EBP-50 or NHERF) is a candidate tumor suppressor gene in human breast cancer." (PMID 18190691, 2008). "The gene encoding Na+/H+ exchanger regulatory factor 1 (NHERF1) is a putative tumor suppressor gene that harbors frequent loss of heterozygosity (LOH) and intragenic mutations in breast carcinoma." (PMID 18190691, 2008). "Using the small interfering RNA (siRNA) method, we demonstrated increased growth of breast cancer cells when NHERF1 expression was knocked down." (PMID 18190691, 2008). "The responses of breast cancer cells to PDGFR inhibition were also altered by changes in NHERF1 expression level." (PMID 18190691, 2008). "Given the critical roles of Akt in cell survival and tumorigenesis, the negative regulatory effect of NHERF1 on Akt activity is highly relevant to NHERF1 mammary tumor suppressor function." (PMID 18190691, 2008). "T47D/NHERF-786 cells showed a more efficient colony outgrowth in soft agar than did either parental T47D (P = 0.0043) or T47D/Babe (P = 0.020) cells, indicating that NHERF1 exhibits growth suppression activity in breast cancer cells." (PMID 17078868, 2006). "In light of the key role of oestrogen in mammary gland development and mitogenic responses of many ER-α-positive breast cancer cells to oestrogen, it seems paradoxical that NHERF1 would act as a tumour suppressor gene in breast." (PMID 17078868, 2006). "Na+/H+ exchanger regulatory factor 1 (NHERF1, also known as EBP-50 or NHERF) is a candidate tumour suppressor gene in human breast cancer." (PMID 17078868, 2006). "Based on a critical role of oestrogen in mammary development and the early-stage progression of breast cancer, NHERF1 was initially postulated as a mitogenic factor, which is not supported by our genetic evidence." (PMID 17078868, 2006). "We used immunoblotting to analyse the expression of NHERF1 in 22 breast cancer cell lines, among which the origin of MDA-MB-435S was under debate." (PMID 17078868, 2006). "We found that the knockdown of NHERF1 in human breast cancer cells led to enhanced growth in either an anchorage-dependent or -independent manner." (PMID 17078868, 2006). "Indeed, in this report we demonstrate that Erbin co-localizes with and is in close physical proximity to HER2, NHERF1 and Ezrin in breast cancer cells, especially within actin-rich membrane protrusions." (PMID 40390040, 2025).